CD8A (CD8 subunit alpha)
Diseases named in the same sentence as CD8A in open-access papers (continued):
Sharing a sentence is not in itself a finding about the gene and the disease.
tumor (continued). "In the CD8-high group, FAP intensity was significantly associated with a higher total tumor density of FoxP3-positive immune cells and a higher ratio of epithelial-to-stromal density of CD8a T cells." (PMID 33153037, 2020). "Consistent with the known role of CD8+ CTLs in limiting cancer development, loss of these cells in mice that lack Cd8α or Beta-2-Microglobulin (a subunit of MHC I complex) both resulted in elevated tumor development in the large intestine." (PMID 31775909, 2019). "Dying or damaged cancer cell–derived DNA can act as a damage-associated molecular pattern sensed by cytosolic cGAS-STING machinery in tumor-associated CD8α+ dendritic cells (DCs), leading to the production of type I IFNs." (PMID 31601678, 2019). "In keeping with previous studies, tumour CD8A expression was significantly associated with TTR in multivariable analysis (HR for each 2-fold increase = 0.86, 95% CI = 0.76–0.97, P = 0.018)." (PMID 31388185, 2019). "Increasing lipid levels and reducing numbers of CD8α+CD4- DCs were associated with increasing tumor burden which was associated with decreasing T cell proliferative responses to tumor antigen presentation in dLNs." (PMID 25886502, 2015). "Firstly, lipid accumulation by tumor-associated CD4+CD8α-, CD4-CD8α- and plasmacytoid DCs implied that these subsets were impaired, however further functional studies such as antigen uptake and presentation assays and migration assays are required." (PMID 25886502, 2015). "The other mechanism observed was the proportional reduction of tumor-associated CD8α+CD4- DCs as tumor size increased." (PMID 25886502, 2015). "The predicted immunogenic mutation count showed a strong relationship with tumor CD8A expression, where tumors with higher numbers of such mutations had higher CD8A expression." (PMID 24782321, 2014). "Their expansion correlates inversely with splenic Breg activity (r=-0.72, P < 0.01) and parallels tumor-associated CD4+CD8a+ T cells that modulate CD8+ T cells via TGF-β1/PD-1 signaling, suggesting conserved immunosuppressive mechanisms across inflammatory contexts." (PMID 40709179, 2025). "We next investigated whether the elevated CD8α+ T cell infiltration into the tumor mass in dKO mice was directly linked to the reduced vascular brain barrier function." (PMID 40408475, 2025). "Additionally,in alternative models of HCC induced by NASH,158 Cd8a-deficient mice developed a higher tumor burden." (PMID 38093838, 2023). "In the presented study, multiple computational tools were used to investigate the roles of CD8A in the pan-cancer study, revealing its essential associations with tumor immune infiltration, immunosuppressive environment formation, cancer progression, and therapy responses." (PMID 36035168, 2022). "In this work, our purpose here is to delineate the roles of CD8A in pan-cancer cohort, whereby revealing its essential associations with tumor immune infiltration, immunosuppressive environment formation, cancer progression, and therapy responses using multiple computational tools." (PMID 36035168, 2022). "Also, the frequency of ZsGreen+ cells in different DC subsets is consistent with previous studies, 32 with a lower frequency of CD8α+ resident DCs bearing tumor-associated antigens (TAAs)." (PMID 33980589, 2021). "Thus, CD8α-specific loss of ALK5 results in higher rates of tumor rejection, improved survival, and enhanced response to radiation." (PMID 32273499, 2020). "IFNs activate CD8α+ dendritic cells to present tumor-associated antigens to CD8+ T-cells." (PMID 32182890, 2020). "Furthermore, the antitumor efficacy of IR towards CT26 colon cancer models was greatly compromised in mice deficient for CD8α+ DCs, indicating the necessity for specialized cross-presenting DC subtypes for ideal tumor control using IR." (PMID 33238631, 2020). "Furthermore, we demonstrate that tumor uptake of CD4+ and CD8a+ specific tracers is overall associated with the tumor growth response to Sym021." (PMID 31754392, 2019).
tumor (continued). "Ranking patients by decreasing CD8A expression and displaying the mutation count for each patient’s tumor revealed a skewed distribution whereby tumors with low CD8A expression had sparse mutations and tumors with high mutation counts were among those with elevated CD8A expression." (PMID 24782321, 2014). "Also, a gene expression signature obtained from tumor biopsies containing the gene (ITGAE) encoding for CD103 among other TIL-related genes (CD8A, CD8B, ITGAE [CD103], PDCD1 [PD-1], CCL5, CXCL13, and IL2) was associated with better outcomes to anti-PD1 therapy." (PMID 38562921, 2024). "Interestingly, authors have also shown that IHC evaluation of CD8 (a co-receptor for the T-cell receptor) resulted in its expression being associated with higher PD-L1 expression, both in the primary tumor and BM, which confirms the ongoing lymphocytic reaction in the BM microenvironment." (PMID 37372340, 2023). "Furthermore, a lower density of YAP1 and FAPα is associated with an increased density of tumor-infiltrating CD8a+ T lymphocytes with a cytotoxic immune signature, implying that fibroblasts may also engage in recruiting regulatory leukocytes to the TME." (PMID 35986369, 2022). "Indeed, the authors used the Cancer Genome Atlas (TCGA) to assess mRNA expression level of PD-L1 and CD8A, confirmed that PD-L1 amplification is associated with active tumor microenvironment immune type I. It was connected with high tumor mutational burden (TMB)." (PMID 31867335, 2019). "This significant increase of cytotoxic cell number indicated that the inhibitory effect of ApoE KO on tumor growth and metastasis may be associated with increase of infiltration of CD8α+ T cells and CD57+ NK cells in urethane-induced lung tumor tissues and lung metastasis tissues." (PMID 31275318, 2019). "Thus, the fact that CD8α− DCs played an equivalent role in cross-presentation of HA tumor antigen in our system might reflect the cell-associated form in which the tumor antigen was delivered." (PMID 20976125, 2010). "125I seeds not only inhibit the growth of TNBC bone metastases and distal tumors but also significantly enhance the infiltration of CD8α+T cells into tumor sites." (PMID 41988184, 2026). "H&E analysis revealed highest cellular density and most disperse extracellular matrix in MTCQ1 tumors with infiltration of CD8a+ T cells in tumor centres and macrophages predominantly peripheral." (PMID 41141655, 2026). "IRF1, IRF9 and STAT1 in lymphoid cells of C1 participated in anti-tumor immune response by impacting target genes CD8A, HLA-A/E, TAP1 and PD-1." (PMID 42074110, 2026). "Mice bearing MTCQ1 tumors were treated with 6 fractions at 2 Gy EBRT and tumor growth and the profile of CD8a+ T cells, CD80+ M1 macrophages, and CD206+ M2 macrophages was investigated." (PMID 41141655, 2026). "Mechanistically, CD8α:MyD88 signaling increased ZAP-70, ERK1/2, JNK, and p38 activation, reducing the response threshold in tumor-specific CD8+ T cells." (PMID 40948803, 2025). "In contrast, the proportions of CD4+ T and CD8α+ T cells within the tumor were extremely low (< 1%)." (PMID 41208884, 2025). "While CD8A expression was higher in fetal‐type tumours, GZMK and SLC4A10 were more highly expressed in embryonal‐type tumours." (PMID 40099956, 2025). "Studies have demonstrated that CD8+ T cells, particularly those expressing CD8a, are pivotal in mediating anti-tumor immunity." (PMID 41583493, 2025). "We construct two evaluation sets: tumour-associated markers (MelanA, S100, gp100, SOX10) and lymphocyte markers (CD20, CD3, CD8a)." (PMID 40842484, 2025). "Reverse transcription–polymerase chain reaction (RT-PCR) in tumor tissue obtained from the mouse tumor model showed increased CD8α expression in the LAA-treated group compared with the control group." (PMID 40076581, 2025). "Tumors displayed heterogeneous immune cell infiltration, with CD45 + cells and CD8a + TILs primarily localized at the periphery of necrotic regions and the tumor capsule." (PMID 39941761, 2025).
tumor (continued). "Our data showed higher CD8α RNA levels in the tumor tissues of mice fed LAA compared with the control group, suggesting that LAA facilitated the intratumoral infiltration of CD8α-positive effector T lymphocytes." (PMID 40076581, 2025). "We correlated MBNL expression across all TCGA cancer datasets with tumor T cell infiltration by either CD8A expression or cytolytic T-cell (CYT) score." (PMID 40305509, 2025). "Tisagenlecleucel consists of a murine scFv of FMC63 monoclonal antibody that binds to CD19 on tumor cells and is fused to the CD8α hinge and transmembrane regions followed by the costimulatory molecule 4–1BB (CD137) and the T cell activation domain CD3ζ chain." (PMID 40061940, 2025). "Cldn5 inhibition lead to an increase in vascular permeability to gadolinium across the brain, with a noticeable increase in CD8α+ cell influx into the tumor microenvironment." (PMID 40408475, 2025). "Our findings revealed that the PR-enriched genes were associated with tumor specific T cells, and PR patients displayed higher abundance of tumor specific T cells, evidenced by elevated levels of CD8A, CXCL13, and IFNG genes." (PMID 41422078, 2025). "Firstly, although lucanthone- and combination- treated tumors significantly increased CD8a + cytotoxic T-cells, both within the tumor core and at the periphery of the tumor, MDI-2268-treated tumors showed the greatest increase in this cell type." (PMID 40684232, 2025). "Mice were treated with CD4- or/and CD8α-specific antibodies at day 19 post tumor inoculation, and then underwent tumor resection at day 21, followed by NK cell therapy during days 24–31." (PMID 39835538, 2025). "Combination therapy with CY12-RP2 and anti-CD8α antibodies dramatically diminished tumor suppression compared to CY12-RP2 alone." (PMID 41573582, 2025). "An example derived through previous manual computation involved productive (killing) recognition of tumors by immune cells: A tumor-killing marker (CD8A) was directed to the tumor-immune cell interaction (immune synapse)." (PMID 39255170, 2025). "A comparative analysis between the two tumor types revealed that MOC2 tumors contained significantly fewer CD8α+ T cells compared to MOC1 tumors, as determined using flow cytometry." (PMID 40282455, 2025). "The administration of L19-IL2 in combination with FOLFOX or as single agent had a potent effect on recruitment and activation of both CD8a+ T-lymphocytes and NK into the tumor front, while those cells where not present in both CTR and FOLFOX treated tumors." (PMID 39773310, 2025). "TIMER (Tumor Immune Estimation Resource) and spatial-omics supported co-localization with tumoral CD8A." (PMID 41300366, 2025). "Consistent with this, spatial transcriptomic analysis using Xenium showed differential localization of T cells (Cd3d, Cd3e, Cd3g, Cd8a, Cd8b1, and Cd4) within tumor sections of RPR2 and CRPR2 mice." (PMID 41353272, 2025). "Second, IHC analysis of CD4 and CD8α indicated that tumor-bearing mice typically had a greater number of these T cells in lymph nodes relative to their tumor-free counterparts." (PMID 41208884, 2025). "The study presented the enhanced antitumor efficacy against weakly immunogenic tumor antigens by CD8+ T cells engineered with a synthetic CD8α:MyD88 fusion protein." (PMID 40948803, 2025). "Specifically, we need to use immunodeficient mice or block CD8+ T cells with CD8a antibodies and subsequently evaluate the effect of L-SeMet on tumor growth to validate this mechanism." (PMID 40141154, 2025). "We further noticed that, 24 h post CpG ODN injection, cd8a:EGFP+ cells with dendrites carried mCherry fragments along the tumor border from the tumor peak to the scale edge." (PMID 41109214, 2025). "CD8A, a glycoprotein primarily expressed on cytotoxic T lymphocytes, which cleave the cytoskeleton and nuclear chromatin, thereby inducing tumor cells apoptosis." (PMID 40547036, 2025).
tumor (continued). "InVivoMab anti-mouse CD8α significantly inhibited the tumour-reducing efficacy of IRT and negated the sensitising effect of propionate on combined radiotherapy and immunotherapy." (PMID 40715695, 2025). "Depletion of CD8+ T cells via administration of monoclonal anti-CD8α (Clone 2.43) overcame the suppression/acceleration of MC38 tumor growth induced by the knock-down/over-expression of MC38-derived Atp6v0a1." (PMID 38971819, 2024). "We noted a significant decrease in tumor-infiltrating CD3e+ T cells (P = .03), CD8a+ T cells (P = .03), and PD-1+ cells (P = .03) in post-ICI samples, compared with pre-ICI samples." (PMID 38207230, 2024). "Tumors with MUC16 mutations exhibit heightened immunogenicity, reflected by an increased proportion of CD8A and Programmed cell death 1 ligand 1 (PD-L1)-positive cells in the tumor microenvironment compared to wild-type tumors." (PMID 38758220, 2024). "A matched scatter plot revealed a consistent inverse correlation between SERPINE1 and CD8A mRNA expression levels (R = −0.555, P < 0.011), in concordance with results obtained from the tumor immune estimation resource." (PMID 38448406, 2024). "The custom mouse panel was designed to detect T cell biomarkers CD3ε, CD4, CD8α and FoxP3 and was evaluated on murine tumor specimens with varying levels of T cell infiltration." (PMID 38605049, 2024). "The tumor infiltrates marked by CD8A and CD14 were then explored as markers representing CTL and TAMC, because they were demonstrated to be their specific markers by scRNA analysis in CRC, respectively." (PMID 38557819, 2024). "We found that mice treated with sorted CD8α– NK cells had lower tumor burden compared with those that received CD8α+ NK cells or no NK cells at all." (PMID 38805302, 2024). "Previous studies have shown that CD8A and CD4 are associated with the presence of CD8+ T cells and CD4+ T cells, respectively, both of which can exert anti‐tumour effects and indicate a better immune therapy response." (PMID 38946232, 2024). "Efficient anti-tumor immune responses require robust and efficient induction of cytotoxic CD8a+ T cells." (PMID 39289872, 2024). "Consistent with previous studies, mice inoculated with CT26 cells and treated with CD8α mAb exhibited CD8+ T cell suppression and a significant increase in tumor burden compared to those treated with IgG2b." (PMID 39107297, 2024). "FOLR1-specific CAR candidates designed with IgG4 hinge (candidates C and G) are associated with slower tumor-killing kinetics, reduced proliferation capacities, and persistency compared to the CAR candidates designed with CD8α hinge (candidates A and E)." (PMID 38254822, 2024). "There were significant differences between any 2 tumor stages, and a higher tumor stage was likely to result in higher CD8A expression." (PMID 38758909, 2024). "The significant increase in splenic CD8α+ T-cell percentages in the chitin + anti-PD-1-treated compared to the untreated 66cl4 tumor-bearing mice was also reflected in the splenic CD8α+ T-cell numbers." (PMID 38605414, 2024). "The results showed that the ratio and density of CD8+ T cells (CD8A+) in the tumour area increased in the OT sample." (PMID 39415331, 2024). "Through univariate Cox regression analysis, nine genes, including 3 oncogenes (HTR3C, CRHR2 and AGTR1), 6 tumor suppressor genes (CD8A, CD3E, SERPIND1, CXCR6, BMX and CD247) were proved to be correlated with the overall survival of EC patients." (PMID 38355782, 2024). "Expression levels of CD68, representing all TAMs, and of CD4 were consistently and highly expressed throughout all stages of tumor progression, whereas CD8A expression was increased in later disease stages." (PMID 38618956, 2024). "In order to shed light on this question, a 4-gene inflammatory signature comprised of CD8A, STAT1, LAG3, and CD274 (encoding PD-L1) was assessed by the RNA-sequencing of the baseline tumor samples of patients included in the CheckMate-816 study." (PMID 39123401, 2024).
tumor (continued). "We chose antibody clones that showed appropriate regional (e.g., splenic white pulp) and subcellular localization (e.g., cell membrane for CD3ε, CD4 and CD8α and nucleus for FoxP3) in spleen and tumor tissue." (PMID 38605049, 2024). "These add-on effects occurred through additional increase in CD8α+ T-cell infiltration and activation in primary tumor and lymphoid organs." (PMID 38605414, 2024). "Surprisingly, even after almost 3 weeks in vivo in the presence of K562 tumor cells and high doses of IL-15, iCD8α+ NK cells had enhanced responses to K562 and cytokine stimulation compared with persistent CD8α– or sustained CD8α+ NK cells." (PMID 38805302, 2024). "Immunohistochemical staining for granzyme B on primary tumor sections corroborated the enhanced CD8α+ T-cell activation in primary tumors upon chitin treatment, albeit only significantly in the 4T1-based model." (PMID 38605414, 2024). "We also confirmed the apoptosis of CD8+ T lymphocyte by analysis of CD8α, TUNEL, and DAPI staining of tumor sections from LCBM patients with EGFR mutation." (PMID 38696655, 2024). "Type I IFN is crucial for the cross-presentation of CD8α+ DC and the development of tumor antigen specific CD8+ T cell in vivo." (PMID 39364399, 2024). "(ii) Quantification of tumor infiltrating CD8a+ cytotoxic T cell relative to the total number of tumor cells." (PMID 38805560, 2024). "After injecting CD8α+ and CD8α–CD56dim NK cells and monitoring tumor kinetics for 19 days, they isolated 3 NK cell populations: sustained CD8α+, persistent CD8α–, and iCD8α+ NK cells." (PMID 39087476, 2024). "The decreased expression of CD8A in T cells in the tumor group concurred with the decreased probability of communicating with B cells and T cells or with the cell population of intra-T cells." (PMID 38448802, 2024). "Perhaps CD8α–CD56dim or iCD8α+CD56dim are favorable for adoptive NK cell therapy in cancer, though additional tumor models need to be tested to prove preclinical efficacy." (PMID 39087476, 2024). "Similar changes were observed in the original Esc tumors, which consistently accumulated fewer Ly6G+ myeloid cells and more CD8a+ lymphocytes than 4662 control and EP tumor tissues." (PMID 38378697, 2024). "Here, we show that sorted CD8α–CD56dim NK cells had superior tumor control in vivo, likely due to enhanced IL-15–induced proliferation." (PMID 38805302, 2024). "In mice inoculated with Ctrl CT26 cells, anti‐CD8α mAb treatment significantly promoted tumor burden compared with that of anti‐IgG2β treatment." (PMID 38229183, 2024). "Patients with positive MOR mRNA expression tended to be classified as tumor microenvironment immune types II, representing low PD-L1 and low CD8A expression." (PMID 37064155, 2023). "These genes included those related to P/DAMP signaling (e.g., Il6, Tlr1, Tlr4, Il1b, Il18), necroptotic tumor cell death (e.g., Casp1, Casp8, Il1b), and activation of the adaptive immune system (e.g., Cd80, Cd8a, Ccr5, Cxcl10)." (PMID 37213298, 2023). "We first analyzed the TCGA dataset and found statistically significant differences in the expression of activated CD4+ memory T cells, CD8a+ in tumor cell infiltration and CD8+T lymphocyte cytotoxic factors in tumor tissues with high/low ISG15 expression." (PMID 37217923, 2023). "Further multiplexed immunofluorescence staining of the CD3/CD4/CD8A/CD68/CCL4 markers validates the immune-activated state in the tumor thrombus samples." (PMID 37244923, 2023). "Next, tumor infiltration by CD8‐positive lymphocytes was analyzed by CD8α staining; CD8‐positive T cells tended to increase on Day 3 after single time DC101 treatment." (PMID 36808261, 2023). "The number of tumor-infiltrating GrB+ effector CD8a+ T cells was highest in mice treated with combinations of αPD-1 plus celecoxib or CAY10678 and somewhat increased in mice treated with αPD-1, celecoxib, or CAY10678 monotherapy." (PMID 37529399, 2023).